EFNA5 (ephrin A5)
Diseases named in the same sentence as EFNA5 in open-access papers (continued):
Sharing a sentence is not in itself a finding about the gene and the disease.
cancer (30 papers, 2006 to 2026). A tumor composed of atypical neoplastic, often pleomorphic cells that invade other tissues. "Considering the inverse contribution of EFNA5 (encoding ephrinA5) to cancer aggressiveness and poor clinical HGSC outcome, we sought to further examine ephrinA5 in HGSC." (PMID 33893375, 2021). "Ephrin-A1 and ephrin-A5 elevated expression in tumorous specimens was linked to decreased survival, while ephrin-B1 overexpression, more frequently observed in high-grade carcinomas, was correlated with an increased recurrence rate and decreased OS." (PMID 34445116, 2021). "For example, LINC00536 and EFNA5 were highly expressed in clusters 1 and 10, which represented two sub-clusters of cancer cells." (PMID 38473208, 2024). "We also compared the resistant subclone C3 to C2 and C4, identifying LMO4 upregulated in C3, a marker of cell proliferation and invasion, and EFNA5 up-regulated in C2 and C4, a gene regulating cancer cells invasion." (PMID 37917660, 2023). "EFNA5 gene expression was found to be upregulated in 13 tumor tissues but downregulated in 15 cancer types." (PMID 36052169, 2022). "As previously shown in cancer cells, ephrin-A5 increased RhoA activity in hippocampal neurons, whereas DAPT significantly increased and caused a synergistic effect on RhoA activation." (PMID 31577226, 2019). "ephrin A5 presents a significantly decrease in cancer, in which it shows an intensive correlation with the co-expression of EphA10s (r=0.558, P=0.004)." (PMID 28427223, 2017). "The mouse models were generated by breeding the ND2-SmoA1 mice (Fred Hutchinson Cancer Research Center, Seattle, WA, USA) used in previous studies with ephrin-A5−/− mice or EphA4−/−EphA7−/− mice." (PMID 26345456, 2015). "Both benign and malignant specimens showed variable ephrin A5 expression with four and eight cancer specimens demonstrating more than 5-fold and 2-fold over-expression of ephrin A5 respectively." (PMID 16737551, 2006). "Previously, EFNA5 was frequently reported as a target gene in various cancers." (PMID 37333453, 2023). "From the results of our analysis, EFNA5 expression was low in most cancers but elevated in CHOL." (PMID 35309935, 2022). "EFNA5, a member of the ephrinA ligand family, is deregulated (up or down) in a variety of cancers." (PMID 36497462, 2022). "Little is known about the exact roles of Ephrin A5 and A7 in cancer progression." (PMID 34572755, 2021). "Due to the effects of IgG-clustered ephrin-A5 stimulation on cancer invasion signaling pathways, like pathothenate and CoA biosynthesis, Rho GTPases and neurotrophin signaling, we sought to investigate whether this would lead a functional outcome." (PMID 32352518, 2020). "EfnA5 regulates focal adhesion, cell motility and cancer invasion via modulation of the actin cytoskeleton, therefore we assessed whether upregulation of EfnA5 upon shBmi1 affected cellular architecture in our model." (PMID 31988455, 2020). "Therefore, based on our literature review, ephrin-A5 is the only molecule from the EPH/ephrin axis that could have a protective anti-cancer role in musculoskeletal sarcomas." (PMID 35563562, 2022). "Signaling between EFNA5 and EPHA is also involved in mediating biological processes such as angiogenesis and cancer." (PMID 40949143, 2025). "In the majority of cancers, EFNA1, EFNA2, EFNA3, and EFNA4 were suppressed by stromal and/or immune components, whereas EFNA5 demonstrated different trends in the stromal and immune scores across different cancers." (PMID 35945523, 2022). "The results showed that EFNA1 and EFNA4 had the highest expression in pan-cancer, followed by EFNA3 and EFNA5 with high expression, and EFNA2 with low expression." (PMID 35309935, 2022). "A positive correlation was noted between the expression of EFNA1, EFNA3, EFNA4, EFNA5 and CNV in most cancer types; however, EFNA2 expression was only weakly correlated with CNV." (PMID 35945523, 2022).
cancer (continued). "Ephrin-B2 expression, contrary to the seemingly tumor suppressive properties of ephrin-A5, was found elevated in CRC samples, with frequent enhancement on the luminal surface of carcinoma epithelium." (PMID 34445116, 2021). "EFNA5 was also highest in CHOL, but low in most other cancers." (PMID 35309935, 2022). "Based on RNA expression data, EFNA1 and EFNA5 were negatively correlated with the stem cell scores in most cancers, whereas EFNA2, EFNA3, and EFNA4 exhibited varying correlations with stem cell scores in different cancers." (PMID 35945523, 2022). "Ephrin A5 does not bind significantly to EphA1 but has been shown to activate EphA2 in human carcinoma cells." (PMID 16737551, 2006).
tumor (26 papers, 2006 to 2025). "In ND2-SmoA1 transgenic mice, loss of ephrin-A5—along with EphA4 and EphA7—significantly reduced tumor size and p-Akt levels." (PMID 41200151, 2025). "A correlation was observed between genotype and tumor size in ephrin-A5 knockout mice with loss of ephrin-A5 resulting in smaller tumors compared to wild-type littermate controls." (PMID 26345456, 2015). "High EFNA5 expression has been linked to poor survival in OC patients although high ephrin levels in general are more frequently associated to favorable clinical outcome due to the transduction of tumor-suppressive signals upon EphA2-Y588 phosphorylation." (PMID 33893375, 2021). "The miR-200 family, particularly miR-200c and miR-200a-3p, has been demonstrated to regulate the ephrin genes EFNA1 and EFNA5, thereby influencing tumor growth and metastasis." (PMID 40004552, 2025). "In contrast, overexpression of either EFNA2 or EFNA5 significantly reduced cell proliferation and migration in vitro and tumor growth in vivo in comparison with control cells, suggesting divergent biological roles among ephrinA family members." (PMID 39964764, 2025). "By enhancing H3K27me3 at the EfnA5 promoter locus, Bmi‐1 regulates and reinforces EfnA5 repression to promote proliferation, invasion, and tumor formation in GIC in both mouse and human models." (PMID 39791545, 2025). "EphA3, an essential regulatory target of ADAM10 through cleaving its primary ligand ephrin-A5, is a member of the receptor tyrosine kinase family, and has been reported to have dual biological effects in tumor progression." (PMID 35551177, 2022). "Using cox regression analysis, we developed a prognostic model in LUAD that included pathological stage, tumor residue, and EFNA5 expression." (PMID 35945523, 2022). "EFNA5 exerts tumor-promoting and suppressive effects in various tumors, which is the center of this work." (PMID 35945523, 2022). "Prior studies have confirmed that the pro-tumor role of ADAM10 is linked to the interaction among ADAM10, EphA3, and ephrin-A5." (PMID 35551177, 2022). "The pathological stage (HR = 2.318, p < 0.001), tumor residue (HR = 2.475, p = 0.004) and EFNA5 (HR = 1.731, p = 0.001) were independent prognostic indicators of LUAD." (PMID 35945523, 2022). "Ephrin-A5 expression, albeit found higher than its EPHA receptors, was significantly reduced in colon cancer tissues and was negatively associated with tumor differentiation and clinical stage." (PMID 34445116, 2021). "We also found that the repression of EfnA5 by Bmi1 contributes to tumour growth in vitro and in vivo in our mouse model." (PMID 31988455, 2020). "EfnA5 mediates Bmi1-dependent proliferation and invasion in vitro and tumour formation in an allograft model." (PMID 31988455, 2020). "Both SNRPD1 and EFNA5 are members of the ‘HALLMARK G2M CHECKPOINT’ gene set, so they participate in cell proliferation and tumour progression via cell cycle arrest at the G2/M‐phase." (PMID 32666642, 2020). "While limited by sample size and variations between animals, these data support the potential role of ephrin-A5 in tumor growth." (PMID 26345456, 2015). "MR imaging revealed reduced tumor growth in ephrin-A5−/−Smo mice compared to the wild-type ephrin-A5+/+Smo control mice." (PMID 26345456, 2015). "EFNA5 inhibits tumor-suppressive signaling pathways, leading to tumorigenesis and drug resistance." (PMID 40567611, 2025). "In addition, the pro-tumor function of EphA3 was reversed by the treatment with the exogenous ephrin-A5-Fc, which increased the phosphorylation level of EphA3 in PC-3 (ephrin-A5 ± ) cells." (PMID 35551177, 2022). "Paradoxically, our previous study on ephrin-A5 expression in PCa tissues showed that 65% (13/20) of PCa tissues were weakly positive or even negative, which is consistent with the expression of ephrin-A5 in other tumor tissues." (PMID 35551177, 2022).
tumor (continued). "These opposing roles may be regulated by its primary ligand ephrin-A5, which induces the phosphorylation of EphA3 receptor and triggers the downstream signal transduction involved in tumor suppression." (PMID 35551177, 2022). "The findings showed higher EFNA5 expression in most tumor tissues." (PMID 35945523, 2022). "In nude mice, ADAM10 accelerated growth of the primary tumor, decreased the level of ephrin-A5 in the tumor tissue, but increased the level of ephrin-A5 in the peripheral blood, accompanied with an increase in the expression of CD31 and VEGF (vascular endothelial growth factor) in the tissue." (PMID 35551177, 2022). "It is concluded that ADAM10-mediated ephrin-A5 shedding promotes PCa metastasis via transforming the role of EphA3 from ligand-dependent tumor suppressor to ligand-independent promoter, and ephrin-A5 in the blood can be used as a new biomarker for PCa metastasis." (PMID 35551177, 2022). "Analytical imaging of NODSCID mice with orthotopically implanted luciferase-tagged mGIC revealed that while 5/9 mice injected with control mGIC developed tumours and silencing of Bmi1 strongly suppressed tumour growth (0/9), concomitant silencing of EfnA5 and Bmi1 rescued tumour incidence (6/9)." (PMID 31988455, 2020). "To understand whether our findings could be translatable to human GBM, we assessed whether a significant correlation existed between BMI1 and EFNA5 expression in human tumours." (PMID 31988455, 2020). "Ephrin A5 preferentially interacts with EphA2, A3, A5, A6, A7 and B2, of which only EphA2 and EphB2 were expressed to any significant degree in the tested normal or tumor samples." (PMID 16737551, 2006). "Notably, only complete ephrin-A5 deletion suppressed tumor progression." (PMID 41200151, 2025). "Thus, ephrin-A5 could have been investigated as a potential tumor-suppressing ligand through the interaction with its tumor promoting receptors such as EPHA2, EPHA3, EPHA4, EPHA5, EPHA7, EPHA8, and EPHB2 in sarcomas." (PMID 35563562, 2022). "Notably, while EFNA1 depletion clearly reduced tumor-suppressive EphA2-pY588, as expected upon depletion of the ligand-mediated signaling, EFNA5 silencing left EphA2-pY588 essentially unaltered in OVCAR3 and even increased this tyrosine phosphorylated receptor in OVCAR4." (PMID 33893375, 2021). "This divergence is evident in our study, in which EFNA2 and EFNA5 overexpression reduced cell proliferation, migration, and tumor growth, in contrast to EFNA1’s tumor-promoting effects." (PMID 39964764, 2025). "The results indicated that EFNA2 expression correlated with tumor residue; the expression of EFNA3 and EFNA4 correlated with age; EFNA5 expression correlated with the number of pack-years smoked." (PMID 35945523, 2022). "As a consequence, pathological stage, residual tumor, and the expression of EFNA2, EFNA3, and EFNA5 had significant prognostic significance in LUAD." (PMID 35945523, 2022). "We next examined the expression of RTK ligands, including HGF, EFNA5, and VEGFA, in the membranes of tumor cells." (PMID 35205843, 2022). "The identification of new RMS-enriched tumor antigens, such as CDH4, Ephrin A5, and A7, support the clinical relevance of using surfaceomics for target discovery and drug development." (PMID 34572755, 2021). "The AB subpopulation also showed a 50-fold copy number amplification of the KRAS locus on chromosome 12p12.1 and two homozygous deletions of the EFNA5 and COL5A4 tumor suppressors." (PMID 25729435, 2015). "In this study, we innovatively illustrated that LINC00607 was markedly downregulated in NSCLC, and LINC00607 suppressed NSCLC cell growth, migration, and invasion via modulating the miR-1289/EFNA5 axis, which indicated that LINC00607 functioned as a tumor suppressor in NSCLC." (PMID 37333453, 2023). "EFNA5, EFNB1 and EFNB2 were found highly expressed in tumor tissues of ESCA." (PMID 37160815, 2023).
tumor (continued). "Whereas EFNB3 showed low expression in cancerous tissues, EFNA2 and EFNA5 expression showed no evident difference between tumor and normal tissues." (PMID 36052169, 2022). "The absence of ephrin-A5 activates EphA3 signaling via ligand-independent pathways that promotes tumor progression." (PMID 35551177, 2022). "Next, we interrogated two independent GBM single-cell RNAseq datasets, and confirmed that a significant number of tumour cells displayed a negative association between BMI1 and EFNA5." (PMID 31988455, 2020). "Unlike the ephrin-A5 mice, data for the EphA4/EphA7 Smo mice did not yield any consistent patterns of variability in tumor size." (PMID 26345456, 2015). "Additionally, both forward and reverse IP experiments revealed no detectable interactions between EphA2 and EFNA2 or EFNA5, suggesting that other receptors and downstream pathways may mediate the tumor-suppressive roles of EFNA2 and EFNA5." (PMID 39964764, 2025). "Of the TCGA datasets, we found that the dataset with the highest number of tumour samples (hthgu133a, n = 548) showed a strong and significant inverse correlation between BMI1 and EFNA5, whilst the other three datasets did not (data not shown)." (PMID 31988455, 2020).
infection (3 papers, 2022 to 2025). The state of being infected such as from the introduction of a foreign agent such as serum, vaccine, antigenic substance or organism. "The EFNA5 and FAS genes were downregulated in MKN-28 cells only after 2-h infection with the H. pylori wt strain." (PMID 37193047, 2022). "Similarly, infection with the Cedar virus pseudotype was positively associated with the expression of EFNB1 and EFNB2 (P < 0.01), but not of EFNA2 or EFNA5." (PMID 39747691, 2025).
neurodegenerative disease (1 paper, 2024). A disorder of the central nervous system characterized by gradual and progressive loss of neural tissue and neurologic function. "As shown by the program results DE miR-3687, miR-612, miR-4261, miR-504-3p, miR-126-5p,and miR-411-5p bind to the mRNA of the B3GNT2, CSMD2, ATN1, CREBBP, ATXN1, EMIN4, and EFNA5 genes, which are associated with neurodegenerative diseases." (PMID 39049823, 2024).
neurologic disease (1 paper, 2023). "Following inoculation of 105 PFU/mouse, approximately 50% of Efna2−/− (m) mice developed neurologic disease, regardless of their Efna3 or Efna5 genotype." (PMID 37202395, 2023).
retinopathy (1 paper, 2020). "The decreased avascular areas indicate that silencing of Efna5 can also protect the retina against retinopathy by enhancing developmental vessel regrowth." (PMID 33102589, 2020). "The expression pattern and biological significance of Efna5 were investigated in a mouse model of oxygen-induced retinopathy (OIR)." (PMID 33102589, 2020).
EFNA5 also shares sentences with these, for which no sentence is quoted: glaucoma (3 papers); Hyperglycemia (2); neurodevelopmental disorder (2); abortion (1); acute lymphoblastic leukaemia (1); Alzheimer disease (1); autism (1); cognitive disorder (1); copy number variation (1); dementia (1); diffuse large B-cell lymphoma (1); endometrial carcinoma (1); genetic diseases (1); glomerular disease (1); human papillomavirus infection (1); Insulin resistance (1); kidney disease (1); liposarcoma (1); mesothelioma (1); microcephaly (1); non-small cell lung carcinoma (1); pancreatic adenocarcinoma (1); peripheral neuropathies (1); primary open angle glaucoma (1); prostate (1); prostate tumors (1); round cell liposarcoma (1); soft tissue sarcoma (1); spina bifida (1); thymoma (1).
A further 3 diseases each share a sentence with EFNA5 in 1 paper.